BCL2 (BCL2 apoptosis regulator)
Diseases named in the same sentence as BCL2 in open-access papers (continued):
Sharing a sentence is not in itself a finding about the gene and the disease.
melanoma (continued). "For instance, up-regulation of BCL-2 has been observed in most melanomas, being correlated with a poor prognosis for patients." (PMID 37047539, 2023). "In particular, we found that, in addition to the well-known anti-apoptotic role, Bcl-2 expressed in melanoma cells is able to increase tumor aggressiveness and to recruit and polarize macrophages in the M2 phenotype." (PMID 37488586, 2023). "In the treatment of melanoma cells, IK can produce ROS, up-regulate the expression of Bax and Bcl-2, inhibit the growth of melanoma cells, and induce apoptosis." (PMID 37570851, 2023). "Among factors able to recruit and polarize macrophages, we previously identified melanoma-specific Bcl-2 protein." (PMID 37488586, 2023). "A study demonstrated increased STAT3 phosphorylation at Y705 in melanoma cell lines cultured in suspension conditions compared to adherent cells, driving upregulation of Bcl-2 and Mcl-1." (PMID 37181747, 2023). "On the other hand, as ornidazole treatment also downregulated the expression of Gli1, it seems reasonable to argue that ornidazole activates the apoptosis through Gli1/Bcl2/Bax-axis in melanoma cells." (PMID 36325671, 2022). "Activated ERK1/2 can regulate the relative proteins involved in proliferation and apoptosis, such as Bad, Bcl-2, and C-myc, thereby contributing to melanoma growth." (PMID 35193614, 2022). "Over the past 25 years in addition to hematological malignancies, elevated Bcl-2 expression and function has been observed in various tumors, including melanoma, breast cancer, colorectal cancer and lung cancer." (PMID 35056993, 2022). "Nur77 is an orphan nuclear receptor that highly expressed in melanoma cells and can interact with Bcl-2 to convert Bcl-2 from an antiapoptotic to a pro-apoptotic protein." (PMID 36686679, 2022). "Further examinations revealed a pro-apoptotic effect, as evidenced by morphological changes in melanoma cells and supported by western blot data showing the downregulation of anti-apoptotic Bcl-2 expression coupled with the upregulation of pro-apoptotic Bax." (PMID 36355533, 2022). "In melanoma, Bcl-2 overexpression increases cell migration, and overexpression of miR-211 in Bcl-2 overexpressing cells can rescue cell migration." (PMID 35912006, 2022). "Since malignant melanoma is characterized by a poor prognosis and resistance to agents inducing apoptosis, the ability of EcTI to reduce BCL-2 and increase BAX confers on these protein-relevant characteristics to sensitize cancer cells to death." (PMID 35566311, 2022). "In a previous study, the authors showed that miR-181a-5p directly targeted and inhibited BCL-2, thereby reducing melanoma stem cells apoptosis and promoting the tumorigenesis of melanoma in vivo." (PMID 35310933, 2022). "It was found that A375 had significantly more early apoptotic cells than keratinocytes, which was consistent with the previous Western blot results showing that BCL-2 apoptotic protein was increased in melanoma." (PMID 35893303, 2022). "MITF can transcriptionally regulate the expression of BCL2 to enable melanoma cell survival, whereas the function of MITF in alternative novel cell modalities, such as ferroptosis, remains elusive." (PMID 36429010, 2022). "Here, we report the ability of PEL and EPI to cause apoptosis in melanoma cells through the contemporaneous increase in pro-apoptotic BAX mRNA expression and decrease in the anti-apoptotic BCL-2, BIRC-5, and MCL1 mRNA expression." (PMID 35877720, 2022). "AXT was proposed to have anti-cancer properties by upregulating proapoptotic proteins (Bax/Bad and PARP) and downregulating anti-apoptotic proteins (Bcl2, p-Bad, and survivin) in colorectal cancer, melanoma, and gastric carcinoma cell lines." (PMID 35204257, 2022).
melanoma (continued). "Lupeol has previously been reported to have the capacity to mediate anticancer activity against melanoma cells by altering the level of Bcl-2, Bax protein, and Wnt/β-catenin signaling." (PMID 35458783, 2022). "In melanoma, it was observed that hypoxia stimulates the anti-apoptotic protein B-cell lymphoma 2 (Bcl-2) which in turn increases VE-cadherin expression." (PMID 36224457, 2022). "lncRNA LHFPL3-AS1-long directly interacts with miR-181a-5p to inhibit the mRNA degradation of BCL-2 (the target of miR-181) in melanoma stem cells." (PMID 35833119, 2022). "We found the lncRNALHFPL3-AS1 hypomethylated in PCa, which has been shown to be upregulated in melanoma and to contribute to tumorigenesis of melanoma stem cells by suppressing apoptosis through inhibition of Bcl-2 mRNA degradation." (PMID 36613831, 2022). "Gli1 and Bcl-2 protein are highly expressed in melanoma A375 cells, and their expressions show a downward trend (P < 0.05) after being treated by cyclopamine." (PMID 35027924, 2022). "At the molecular and cellular levels, curcumin inactivates EMT cascade and affects many targets involved in melanoma initiation and progression (e.g., BCl-2, MAPKS, P21, and some microRNAs), which emerge with great potential for clinical applications." (PMID 35585935, 2022). "It was reported that melanoma cells show higher basal expression of anti-apoptotic Bcl-2 proteins including MCL-1, Bcl-2 and Bcl-xL." (PMID 33523262, 2021). "Here, we show that cytotoxicity of the TRAIL-expressing oncolytic adenovirus AdV-TRAIL can be significantly improved in TRAIL-resistant and TRAIL-sensitive melanoma cell lines by silencing of the antiapoptotic Bcl-2 protein Mcl-1." (PMID 34028599, 2021). "One of the possible signaling pathways of RAC1 in the promotion of melanoma is through its binding to Bcl-2." (PMID 34827551, 2021). "After treatment with complex 1,BCL-2 transcript levels were downregulated in melanoma B16F10 in both tested concentrations." (PMID 34961767, 2021). "The involvement of Bcl-xL in melanoma progression was also proved by Liqing Zhuang’s group via immunohistology analysis of Bcl-xL and other anti-apoptotic proteins, as Bcl-2 and Mcl-1, in sections of benign nevi, primary melanoma and metastatic melanoma." (PMID 33803452, 2021). "Western blot analysis showed that the expression level of Bcl-2 decreased in infected melanoma cells." (PMID 34835533, 2021). "Bcl-2 siRNA would inhibit Bcl-2 expression, allowing melanoma cells to respond to the action of DP1, thereafter inducing apoptosis as well as senescence." (PMID 34064748, 2021). "The downregulation of BCL-2 and the upregulation of Caspase 3 observed in melanoma B16F10 cells indicate that these cells underwent apoptosis after complex 1 treatment." (PMID 34961767, 2021). "Prior studies into the carcinogenesis of melanoma has revealed the critical role of the Bcl-2 proteins and their capacity to confer apoptotic resistance to melanoma cancer cells." (PMID 33478104, 2021). "For example, the overexpression of anti-apoptotic Bcl-2 in human melanoma cells leads to resistance to many cytostatic drugs." (PMID 34617137, 2021). "Application of 5′ppp-siRNA for Bcl-2 in malignant melanoma resulted in inhibition of tumor growth due to, among other things, downregulation of Bcl-2." (PMID 34948194, 2021). "Previous studies reported similar findings that DAPs GO-Y030 and DM1 decreased bcl-2 protein concentration in colon cancer and melanoma cells, respectively." (PMID 34299042, 2021). "Overexpression of RAC1 in melanoma cells increased ROS levels that inhibited PP2A preventing thereby dephosphorylation of Bcl-2." (PMID 34827551, 2021).
melanoma (continued). "Combined inhibition of MCL-1 and BCL-xL by S63845/S64315 plus Navitoclax or the combination of MCL-1 and BCL-2 by S63845/S64315 plus ABT-199 synergistically induces extensive death in advanced/refractory melanoma cell lines both in vitro and in vivo." (PMID 33883020, 2021). "The importance of Bax in relation to Bcl-2 in the resistance to TRAIL in melanoma is supported by a series of studies." (PMID 34299249, 2021). "The same authors then decided to combine gene therapy and chemotherapy by the association of Bcl-2 siRNA and stealth DP1-loaded LNCs to treat SK-Mel28 melanoma cells." (PMID 34064748, 2021). "MCL-1 depletion significantly induced apoptosis in melanoma cells and resensitized mutant BRAF melanoma cells to anoikis compared with depletion of BCL-2 or BCL-xL." (PMID 33883020, 2021). "We previously demonstrated that antisense oligonucleotides against both Bcl-xL and Bcl-2 were able to inhibit angiogenesis in melanoma cell lines overexpressing Bcl-2." (PMID 33803452, 2021). "MITF also regulates some genes that are important for melanoma survival (e.g., BCL2), proliferation (e.g., CDK2) and metastatic potential (e.g., c-MET)." (PMID 33746605, 2021). "This study also shows a clear dissociation between changes in Bcl-2 expression (downregulation) and Bcl-xL or Mcl-1 expression (upregulation) during progression of melanoma." (PMID 33803452, 2021). "The resistance of B16F10 melanoma cells to CTND was terminated by silencing the cellular Bcl-2 gene via RNA interference, and the therapeutic efficacy was significantly enhanced." (PMID 34163720, 2021). "Patients randomly received oral BSE (standardized for 50, 100, or 200 μmol SFN) daily for evaluation of its effect on melanoma risk marker STAT3 as well as proliferative marker Ki-67 and apoptotic marker Bcl-2." (PMID 34638282, 2021). "Similarly, we also observed a decreasing level of Bcl-2 in Fyn deficiency and Lj-1-60 treated melanoma cells, which may explain why inactivated Stat3 cannot translocate into the nucleus and bind to the Bcl-2 promoter, thus decreasing the transcription of Bcl-2." (PMID 32565740, 2020). "THP-1 monocytic cells, monocyte-derived macrophages and melanoma cells expressing different levels of bcl-2 protein were used." (PMID 32269145, 2020). "Our data demonstrate, for the first time, a synergy among bcl-2 overexpressing melanoma cells and cellular components of tumor microenvironment." (PMID 32269145, 2020). "Bcl-2, a pro-apoptotic protein, regulates the expression of MIR211 by modulating MITF expression in melanoma cell lines, in addition to the reciprocal regulation of BCL2 by MITF." (PMID 33628737, 2020). "The further analyses showed that LHFPL3-AS1 promoted tumorigenesis of melanoma stem cells by suppressing the Bcl-2 degradation." (PMID 33149126, 2020). "The combination of BH3 mimetics targeting different anti-apoptotic proteins such as Bcl-2 and Mcl-1 or Bcl-xL and Mcl-1, has been reported to shown significant benefit for the treatment of melanoma." (PMID 32455818, 2020). "In this regard, this function of BCL2L10 is similar to that of BCL2, Bcl-xL, and MCL1 since they are both abundantly expressed in melanoma and implicated in cisplatin resistance." (PMID 33396645, 2020).
melanoma (continued). "In a murine melanoma model, a BCL2-specific 3p-siRNA, designed to silence the anti-apoptotic BCL2 gene and stimulated RIG-I-mediated production of type I IFNs, was reported to lead massive apoptosis in lung metastasis." (PMID 33121210, 2020). "Recently, the ERDR1 protein was found to enhance apoptosis in melanoma cells by regulating Bcl-2 and Bax expression, providing evidence for its critical role in the suppression of melanoma progression." (PMID 32283647, 2020). "Overall, our study supports the rationale for combining an MCL1 inhibitor with a BCL2 inhibitor as a therapeutic option in patients with advanced melanoma." (PMID 32764384, 2020). "Oregano extract was able to trigger apotosis in the human melanoma cells by increasing Bax and Cycs concentrations and decreasing Bcl-2 and pro Casp-3 amounts." (PMID 33080917, 2020). "Short-interfering RNA (siRNA)-mediated silencing of Bcl-2 expression can markedly inhibit vasculogenic mimicry in melanoma under hypoxic conditions." (PMID 32993787, 2020). "Since PGE2 induces M2 macrophage polarization, and COX-2-dependent PGE2 production impairs recruitment and activation of immune cells, we investigated the effects of bcl-2 on the expression of COX-2/PGE2 by melanoma cells." (PMID 32269145, 2020). "Western blot results indicated that the LHFPL3-AS1-long overexpression increased the BCL-2 expression in melanoma stem cells." (PMID 33149126, 2020). "In melanoma cells with strong BCL-2 expression, the addition of ABT-737 to co-culture with expanded peripheral blood cytotoxic T-lymphocytes amplified tumor cell kill." (PMID 32131385, 2020). "Our previous studies have demonstrated that bcl-2 affects melanoma progression and regulates the tumor microenvironment." (PMID 32269145, 2020). "To expand these findings, we generated BCL-2 deleted B16F10 murine melanoma cells using CRISPR/Cas9 genome editing." (PMID 32792521, 2020). "In melanoma, knocking down BCL2 sensitized cells to the MCL1 inhibitor S63845, and conversely knocking down MCL1 sensitized cells to the BCL2 inhibitor ABT-199." (PMID 32764384, 2020). "The in vitro and in vivo results showed that LHFPL3-AS1-long directly interacted with miR-181a-5p to inhibit the mRNA degradation of Bcl-2 (the target of miR-181), thus suppressing apoptosis of melanoma stem cells." (PMID 33149126, 2020). "We previously reported Bcl-2 ability to regulate the expression of miR-211 and miR-204, two miRNA involved in melanoma progression and resistance." (PMID 32060259, 2020). "From this, the protein data showed that FKB treatment reduced the expressions of Beclin-1 and Bcl-2 proteins dose-dependently and led to autophagy in melanoma cells." (PMID 33053749, 2020). "We and others have previously shown that most melanoma cell lines express the major anti-apoptotic BCL2 family member proteins, such as BCL2, MCL1, and BCLXL10–15." (PMID 32513939, 2020). "Previous reports showed that H2S donors inhibit the activity of NF-κB and decrease the expression of anti-apoptotic proteins such as Bcl-2 to induce spontaneous apoptosis of human melanoma cells." (PMID 31949127, 2020). "High expression of Bcl-2 is correlated with resistance to chemotherapy in human melanomas and other tumors." (PMID 32977329, 2020). "It has been reported that the expression level of BCL-2 is increased during the development and progression of melanoma." (PMID 32858528, 2020). "In agreement, the number of melanoma-infiltrating macrophages in vivo was increased, in parallel with a greater expression of bcl-2 in tumor cells." (PMID 32269145, 2020). "Our results also confirmed up-regulation of Bax and caspase-3 and down-regulation of Bcl-2 in melanoma of mouse models after administration of IL-24-iMSCs, demonstrating that IL-24 contributed to the anti-tumor effects of IL-24-iMSCs." (PMID 32015693, 2020). "In this context, the influence of the interactions between LHFPL3-AS1, miR-181 and Bcl-2 on apoptosis of melanoma stem cells was further evaluated." (PMID 33149126, 2020).
melanoma (continued). "The levels of expression of PARP, caspase-3, and dysregulated ratio of Bax/Bcl-2 showed that FKB significantly induced the apoptotic cell death mechanism in melanoma cells with the caspases playing a crucial role." (PMID 33053749, 2020). "Further, the bcl-2 network is found dysregulated in melanoma, where high bcl-2 levels account for cancer stem cells mediated therapeutic resistance to apoptosis and poor prognosis." (PMID 32269145, 2020). "Conversely, nilotinib also suppresses the STAT3 pathways that can lead to a reduction in BCL2 expression that acts in concert with BIM induction to trigger an apoptotic response and cell death in KIT-mutated melanoma." (PMID 32344828, 2020). "In particular, melanoma cells expressing high levels of bcl-2 displayed enhanced activation of the IL-1β/COX-2 axis, which paralleled an increased gene expression and secretion of IL-8, IL-17 and CCL2." (PMID 32269145, 2020). "We also evaluated the effect of CM derived from melanoma cells after silencing of bcl-2 with siRNA (si-bcl-2) on M-DM polarization." (PMID 32269145, 2020). "In subsequent studies, increased Bcl-2 expression has been reported in many different solid tumor histotypes, including ovarian, breast and lung carcinoma, and melanoma." (PMID 32455818, 2020). "It has been observed that Erdr1 induces murine melanoma apoptosis through the regulation of Bcl-2 and Bax." (PMID 33644036, 2020). "Taken together, our results show that melanoma-specific bcl-2 controls an IL-1β-driven axis of macrophage diversion that establishes tumor microenvironmental conditions favoring melanoma development." (PMID 32269145, 2020). "In vitro studies were supported by in vivo experiments demonstrating that oral gavage of isoegomaketone in mice subcutaneously carrying B16 melanoma inhibited tumor growth, induced apoptosis, as well as increased Bax/Bcl-2 ratio." (PMID 32948083, 2020). "In conclusion, our study is the first demonstration of an antitumor activity of OA by controlling the altered pattern of gene expression (transcripts and miRNAs) related to mTOR and BCL2 pathways in melanoma cells." (PMID 33071785, 2020). "At the same time, the expression of cleaved Caspase-3, in melanoma cells upon siG9a transfection increased significantly according to Western blot analysis, while the expression of Bcl-2 was remarkably reduced." (PMID 32015216, 2020). "To validate our results in an immunocompetent context and to assess the effect of bcl-2 expression on T cells, we injected B16/F10 murine melanoma control and bcl-2 overexpressing cells in C57/Bl6 mice." (PMID 32269145, 2020). "TAP-nanoemulsion triggered apoptosis of human malignant melanoma in the lung by inhibiting Bcl-2, cyclins D1 and E, NF-κB, ERK, MEK, and MMP-1 and MMP-9 and increasing cleaved caspase-9 and caspase-3, ATM, and p21." (PMID 32908627, 2020). "This resulted in increased production of IL-6 by IL-17 receptor-expressing tumor and tumor-associated stromal cells and concomitantly increased STAT3 signaling and production of pro-survival Bcl-2 and Bcl-xL in melanoma cells." (PMID 32517051, 2020). "Collectively, these findings demonstrated that LHFPL3-AS1-long directly interacted with miR-181 to inhibit the mRNA degradation of Bcl-2 (the target of miR-181), thus suppressing apoptosis of melanoma stem cells." (PMID 33149126, 2020). "As TRAIL-induced apoptosis in melanoma cells and Smac release are essentially controlled by Bcl-2 proteins, the targeting of antiapoptotic Bcl-2 proteins appears as an important strategy for enhancing TRAIL sensitivity." (PMID 31083589, 2019).